SNORA50A (small nucleolar RNA, H/ACA box 50A )
Synonyms: ACA50; SNORA50; SNORA76A
Gene: Small nucleolar RNA gene on chromosome 16 (58,559,796 to 58,559,931, reverse strand). Ensembl gene ENSG00000281910.
Gene Ontology:
Biological process: RNA processing
Cellular component: nucleolus
Homologues: Orthologues: chimpanzee SNORA50A (100% identical), macaque SNORA50A (100% identical), dog SNORA50A (99% identical), guinea pig SNORA50A (99% identical), rabbit SNORA50A (99% identical), pig SNORA50A (99% identical), mouse Gm26265 (96% identical), rat LOC120098682 (78% identical).